EGFR (epidermal growth factor receptor)
Diseases named in the same sentence as EGFR in open-access papers (continued):
Sharing a sentence is not in itself a finding about the gene and the disease.
cancer (continued). "With advances in cancer genomics, a group of genes has been identified as drivers of LUAD, including mutations in the epidermal growth factor receptor (EGFR), c-MET, KRAS, and anaplastic lymphoma kinase (ALK)." (PMID 37511958, 2023). "EGFR was a driver of many tumorigeneses, and a target of many cancer treatments currently used in clinical practice." (PMID 37420173, 2023). "Growth factors also promote micropinocytosis, such as that induced by EGFR signaling in cancer cells expressing Ras." (PMID 37046653, 2023). "We discovered that MDM2, PTGS2, EGFR, and VEGFA are the key genes regulated by JCF and closely associated with the development of cancer." (PMID 37361218, 2023). "EGFR overexpression has been observed in several types of cancer, including non-small cell lung cancer, pancreatic cancer, glial cell carcinoma, and other tissues." (PMID 38005329, 2023). "To test this assumption, we used A431 cancer cells, which are known for their high level of EGFR expression, and in which we had already demonstrated the mitochondrial localization of MNT1." (PMID 38140028, 2023). "We then compared amplifications around MYC, ERBB2 and EGFR in the whole chromosome view in corresponding highly amplified cancer tissues." (PMID 37298484, 2023). "The efficacy of EGFR targeted cancer therapies is obstructed by two major challenges: acquired and innate resistance towards the available drugs." (PMID 37446288, 2023). "In this regard, activation of GPER has been shown to play a role in the activation of the EGF receptor (EGFR) in cancer cells, which provides insight into its potential role as a regulator of angiogenesis in placental development." (PMID 37393260, 2023). "Our findings highlight the association between EGFR expression and temozolomide efficacy, and demonstrate how CRISPR/Cas9-based targeting of enhancers can be used to modulate the expression of key cancer genes." (PMID 37803333, 2023). "To bridge this gap in knowledge, we conducted a retrospective cohort study focused on patients with EGFR-mutant cancers that had transformed into SCLC." (PMID 38188289, 2023). "This analysis revealed activation of kinases routinely associated with other RTKs (e.g., ALK, EGFR, RET) in cancer." (PMID 37587872, 2023). "Currently, there are many mAbs available on the market that target different cancers, such as Trastuzumab, Pertuzumab, and Margetuximab for HER2+ cancers, Rituximab for non-Hodgkin’s lymphoma, and Cetuximab for EGFR+ colorectal cancer." (PMID 37638058, 2023). "Taken together, we present the in vitro characterization of a novel bispecific antibody that re-activates T cell immunity in EGFR-expressing cancers through targeted co-stimulation of CD27." (PMID 37545491, 2023). "More clinical trials are needed to verify the therapeutic utility of EGFR pathway inhibitors in cancer cases involving chromothripsis." (PMID 36761982, 2023). "AnxA6 displays cancer suppression effects on A431 cells by interacting with protein kinase Cα (PKCα) to reduce EGF-induced tyrosine phosphorylation of EGFR (pY-EGFR) and cycling D1 expression." (PMID 37528485, 2023). "The activation of the epidermal growth factor receptor (EGFR) has been shown to enhance the formation of tumourspheres, a defining trait of cancer stem cells (CSCs)." (PMID 37368660, 2023). "Common EGFR inhibitors used in cancer treatment include anti-EGFR mAbs, such as cetuximab and panitumumab, EGFR TKIs like gefitinib, erlotinib, and afatinib, as well as HER2 mAbs trastuzumab and pertuzumab, and HER2 TKI lapatinib." (PMID 37614311, 2023). "It seemed that the molecular features of EGFR‐LFD carriers were different among different types of cancer." (PMID 36622089, 2023). "Such a process has been noted for one of the most frequently overexpressed receptors in cancer, the epidermal growth factor receptor (EGFR), and for some other tyrosine kinases." (PMID 36986848, 2023).
cancer (continued). "The link between DAPK (death-associated protein kinase) promoter methylation and acquired resistance to anti-EGFR TKIs was investigated for the first time by Ogawa T and collaborators in a collection of cancer cell lines." (PMID 37152062, 2023). "Tyrosine kinase inhibitors such as gefitinib, erlotinib, neratinib, afatinib, dacomitinib, and osimertinib and monoclonal antibodies such as cetuximab, panitumumab, nimotuzumab, and necitumumab are used for treatments in cancers with EGFR dysregulation." (PMID 38137520, 2023). "Although novel c-MET (capmatinib, tepotinib) and EGFR inhibitors (osimertinib, lazertinib) have received limited approval for the treatment of various cancers, their high cost limits patient accessibility, particularly in the developing world." (PMID 37924112, 2023). "EGFR/FAK/NF-kB is reported as an important signaling pathway utilized by cancer cells to resist cisplatin." (PMID 36715825, 2023). "Integrins and EGFR share similar signaling pathways, allowing cancer cells to adapt and withstand therapy more effectively." (PMID 36835536, 2023). "Our analysis revealed that EGFR‐LFD accounted for 0.03% of all cancer cases, which was extremely rare." (PMID 36622089, 2023). "Another example of EGFR-targeted therapy is the modification of donor cells with a vector encoding the GE11 peptide (YHWYGYTPQNVI), which shows high affinity for EGFR-overexpressing cancer cells." (PMID 37686050, 2023). "Erlotinib is a targeted inhibitor of the epidermal growth factor receptor (EGFR), which is crucial for cancer proliferation." (PMID 37238181, 2023). "With the EGFR protein, a significant contributor to cancer proliferation and survival due to its tyrosine kinase activity, Isolariciresinol interaction at the Asp A:855 residue holds therapeutic significance." (PMID 37964873, 2023). "The EGFR is expressed in healthy and cancer epithelial cells and plays a crucial part in the biological process of tumor development." (PMID 37927605, 2023). "Although EGFR TKIs initially have an outstanding therapeutic effect, most cancers exhibit resistance to EGFR TKIs, which is inevitable." (PMID 37951898, 2023). "The effect of DOXA on TNBC cell lines in vitro was evaluated in terms of cell viability, apoptosis, c-MET/EGFR signaling pathway, molecular docking studies and impact on cancer stem cell (CSC)-like properties." (PMID 37924112, 2023). "These two antibodies are known binders for cancer therapeutic targets epidermal growth factor receptor (EGFR) and programmed death ligand 1 (PD-L1), respectively." (PMID 37592990, 2023). "Antitumor activity with minimal skin toxicity for nimotuzumab relative to other anti-EGFR drugs has been reported for specific cancer types." (PMID 37762316, 2023). "We highlight the shortcomings of the EGFR inhibition strategy in cancer treatment, leading to the need to develop an alternative strategy called targeted protein degradation (TPD)." (PMID 37754201, 2023). "Profiling was carried out using Duplex-seq, which covers a broader range of mutations (EGFR exon 18, 19, 20 and 21, KRAS exon 2 and 3 and other cancer genes)." (PMID 37020004, 2023). "Li applied a multifunctional AuNPs probe based on the anti-EGFR Apt-and anti-EGFR antibody (Ab) to EGFR-positive cancer cells." (PMID 36769237, 2023). "Here, we investigated the frequency and mutation spectrum of EGFR‐LFD using targeted sequencing in a large cohort of 66,500 Asian pan‐cancer cases." (PMID 36622089, 2023). "Targeting ALK and EGFR can effectively improve the quality of life and survival time of cancer patients." (PMID 36903251, 2023). "Recent reports have shown that paclitaxel can also inhibit the proliferation of cancer cells through the EGFR/MAPK signaling pathway." (PMID 36845692, 2023). "The activation of EGFR has been widely proven to promote cancer progression, metastasis, recurrence, and drug resistance." (PMID 36841806, 2023).
cancer (continued). "Second, internalized EGFR has prosurvival functions in cancer cells that are kinase-independent and, thus, unaltered by current tyrosine kinase targeting therapies." (PMID 37756411, 2023). "So far, the EGFR inhibition has been established a major therapeutic target in cancer therapy, particularly for tumors of breast, cervix, ovaries, kidney, esophagus, prostate and NSCLC." (PMID 37528485, 2023). "In line with this, the paradoxical effects are remarkable, since a positive correlation was observed between the overall survival period of patients with several cancers and EGFR overexpression in tumor cells." (PMID 38006033, 2023). "Supporting these data, the promotion of tumor cell invasiveness and EMT in cancer cells by the EGFR/ErbB family has previously been reviewed and observed in various cancers." (PMID 38255679, 2023). "Multispecific quenchers of the several soluble ligands of the EGF receptor (EGFR) are needed for broad inhibition of EGFR signaling and can serve as a new therapeutic modality for several types of cancer." (PMID 37671023, 2023). "Extensive research into the reasons of drug resistance highlighted the high complexity of EGFR signaling and regulation during cancer cell progression and interaction with the microenvironment." (PMID 37114127, 2023). "In another study, the combination of CUR and CIS improved the sensitivity of A549 cells to X-rays, reducing cancer growth most likely by blocking Epidermal Growth Factor Receptor (EGFR)-related signaling pathways." (PMID 37175156, 2023). "EGFR, originally identified as a cancer-promoting protein, is now known to be involved in a multitude of (patho)physiological phenomena, including functional hyperemia in the brain." (PMID 38003472, 2023). "Taken together, CD27xEGFR has anti-cancer activity both by co-stimulation of T cells at the sites of EGFR expression as well as by directly blocking EGFR on cancer cells." (PMID 37545491, 2023). "Patients with EGFR-TKIs-acquired resistant cancers have high levels of phosphorylated STAT3 to some extent." (PMID 37089959, 2023). "In short, IGF2BP3 plays an oncogenic role in stabilizing EGFR mRNA in an m6A-dependent manner and further regulates cancer cell proliferation and drug resistance to cetuximab in CRC cells." (PMID 37658049, 2023). "This combination medication targeted and killed cancer cells with platinum-based drugs while blocking EGFR-related signal transduction in cells with high EGFR expression, achieving multi-drug combination therapy." (PMID 37609372, 2023). "The cross-reactivity of 7D12 was further validated using flow cytometry on two cancer cells expressing either human or canine EGFR." (PMID 37781693, 2023). "As expected, Gefitinib, an inhibitor of EGFR approved for the clinical treatment of cancers, induced a dose-dependent reduction of the cell viability in MDA-MB-231 cells, and this is attenuated by the enforced expression of PELI1." (PMID 36841821, 2023). "EGFR exerts a vital role in normal cellular growth and differentiation, and its disorder is found in the pathogenesis of many cancers." (PMID 37132043, 2023). "Overexpression of EGFR promotes cell proliferation, cell invasion, angiogenesis, and prevention of cancer cell apoptosis via the dysfunction of downstream signaling involving PI3K, Ras-Raf-MAPK, and JNK." (PMID 36810560, 2023). "In this context, four phytochemicals Curcumin, derived from Curcuma longa; Resveratrol, from Vitis vinifera; Quercetin, from Sophora japonica; and Pepperlongumene, from Piper longum, were studied and tested against cancer as a part of the EGFR-TKIs class." (PMID 37128337, 2023). "Cancer cells exhibit highly activated signaling pathways like EGFR, VEGFR, and their downstream pathways such as PI3K/Akt/mTOR." (PMID 37174125, 2023). "Outside of recycling logistics for monomers, most research on EGFR recycling and signaling has been conducted in the context of benefitting cancer growth and progression, as discussed later." (PMID 37752992, 2023).
cancer (continued). "Previously, we discovered that autophagy-mediated EGF secretion contributed to the hyperactivation of EGFR signaling, thereby triggering resistance to anti-cancer treatment." (PMID 37165076, 2023). "Some anti-cancer drugs have been developed and applied in clinical cancer therapies by targeting genes such as EGFR, KRAS, etc.." (PMID 36833194, 2023). "Among the members of the ERBB family, HER2, and EGFR are often highly expressed in multiple cancers." (PMID 35822637, 2023). "For example, EGFR NES mutants with increased nuclear accumulation promote the aggressiveness of cancer cells, including TKI resistance." (PMID 37081749, 2023). "The action of gefitinib is inhibited as a result of its ability to slow or stop the proliferation of cancer cells, as a result of its ability to inhibit mutant EGFR proteins." (PMID 38532833, 2023). "The pathogenesis of malignant glioblastoma (GB) is attributed to the over-expression of epidermal growth factor receptor (EGFR) and EGFR variant III (EGFRvIII) in a host of cancer types." (PMID 37020537, 2023). "The p27 protein, a cyclin-dependent kinase (CDK) inhibitor and a negative regulator of cell cycle control, is a crucial downstream effector of the EGFR tyrosine kinase inhibitor (TKI)-mediated growth blockage in cancer cells." (PMID 36611972, 2023). "According to the confocal microscopic analyses and biodistribution assay, iEDNs showed a higher accumulation in EGFR-positive MDA-MB-231 cancers in vitro as well as in vivo, compared to untargeted EDNs." (PMID 36839675, 2023). "In this review, we discuss the different functions of EGFR in cancer and AD and the potential of EGFR as a dual molecular target for AD diseases." (PMID 37601068, 2023). "Currently, various tyrosine kinase inhibitors or monoclonal antibodies that inhibit EGFR have been developed and used as therapeutic agents for cancers like non-small cell lung cancer and metastatic colorectal cancer." (PMID 36737605, 2023). "Approximately two decades have passed since researchers began investigating the limited anti‐cancer effect of EGFR‐targeted therapeutics in cancer." (PMID 37341071, 2023). "These exosomes showed low mitogenic activity and a high affinity for EGFR-overexpressing cancer cells; thus, they were demonstrated as part of a tailor-made delivery system for EGFR-targeted therapy." (PMID 37345176, 2023). "The applications centered on EGFR are the most promising and advanced used at the clinical level among recent developments in molecular targeted cancer therapy." (PMID 36768973, 2023). "It is believed that MET overexpression leads to EGFR-TKI resistance in cancer patients, and more needs to be understood about the relationship between MET and EGFR." (PMID 37754956, 2023). "Abnormal, enhanced expression of EGFR triggers a series of intracellular signals, ultimately leading to the proliferation of cancer cells, induction of angiogenesis, and metastasis." (PMID 37658049, 2023). "Recent studies have shown the promise of ferroptosis-inducing therapy in EGFR-TKI resistant cancer cells." (PMID 36760347, 2023). "Recent studies have shown the EGFR/AKT/mTORC1 signaling pathway plays a crucial role in HPV-induced cancers." (PMID 37947608, 2023). "The EGFR is a receptor tyrosine kinase that is involved in cell proliferation, survival, differentiation, and migration invasion and metastasis of various cancer types." (PMID 37685910, 2023). "In vitro photoacoustic microscopy demonstrated significant uptake and contrast enhancement only in EGFR/ErbB2-positive cancer cells compared to benign cells after incubation with the nanoparticles." (PMID 37998152, 2023). "The human epidermal growth factor receptor (HER) family of receptors occupies a central position in the development of various human cancers." (PMID 38067203, 2023). "For a great example, mutant KRAS and mutant EGFR were found in EVs and transferred to recipient cells leading to cancer progression." (PMID 36671802, 2023).
cancer (continued). "Corn silk crude polysaccharide inhibits the EGFR/PI3K/AKT/CREB signaling pathway to exert its antipancreatic cancer activity." (PMID 37233483, 2023). "The knowledge gained here challenges the current understanding of EGFR signaling in health and disease and opens avenues for the exploration of biased inhibitors as anti-cancer therapies." (PMID 37989743, 2023). "Most EGFR mutations harbor an exon 19 deletion (ex19del) or exon 21 L858R in NSCLC, both of which render cancer sensitive to EGFR TKIs." (PMID 37951898, 2023). "Multiple mechanisms of gefitinib resistance have been reported, including the EGFR T790M mutation, MET amplification, ERBB2 amplification, and cancer phenotypic transformation." (PMID 36760347, 2023). "EGFR is a transmembrane protein that can transduce signals via translocation to intracellular organelles upon stimulation of various cancer cells, in addition to its canonical receptor tyrosine kinase activity." (PMID 37461111, 2023). "With this in mind, the present study has focused on an untapped potential of Cannabis sativa L. based phytochemicals to develop a new generation of EGFR-TKIs with therapeutic applications for cancer and other diseases that are currently untreatable." (PMID 37128337, 2023). "Cetuximab has activity in other EGFR expressing cancers and enhances the effectiveness of radiotherapy." (PMID 37417890, 2023). "Cav-1 can also promote the binding of epidermal growth factor receptor (EGFR) to the kinase domain of the Caveolin binding motif and act as a pro-cancer factor to activate EGFR-mediated mitosis initiation." (PMID 37828916, 2023). "Interesting articles have identified bacterial infections at cutaneous toxicity sites in approximately one-third of cancer patients treated with EGFR inhibitors, and most of these patients also had a positive blood culture for Staphylococcus aureus." (PMID 36990917, 2023). "EGFR protein is involved in the development and spread of cancer and also contributes to chemotherapy and radiotherapy resistance." (PMID 37627119, 2023). "Combining all the cancer types, EGFR‐LFD was identified at a rare ratio of 0.03% (17 out of 66,500)." (PMID 36622089, 2023). "Evidences from genetic manipulation studies show GSTP1 facilitates cell viability and increases resistance to cisplatin and targeted therapy including gefitinib, erlotinib, or afatinib for the relevant EGFR mutated, and crizotinib for ALK translocated cancers." (PMID 36709476, 2023). "In this paper, we aimed to summarize the current research identifying changes in the mesenchymal-epithelial transition (MET) gene that occur after EGFR-targeted therapy, allowing the cancer to become resistant." (PMID 37296959, 2023). "As a transmembrane tyrosine kinase, therapeutic interventions for EGFR-driven cancers have largely focused on targeting via monoclonal antibodies and tyrosine kinase inhibitors (TKIs)." (PMID 37720348, 2023). "It has been reported that miR-7-5p attenuates the activation of ERK signaling and induces cell cycle arrest and cell death in cancer cells by down-regulating EGFR expression." (PMID 37114127, 2023). "Cancer cells have several mechanisms to trigger the network at various stages of the EGFR signaling pathway, that is, ligand overproduction, receptor overproduction, or constitutive stimulation of EGFR receptors." (PMID 38090376, 2023). "Despite improvements in cancer therapy strategies, only a minority of patients have benefited from EGFR-targeted monotherapy." (PMID 37438719, 2023). "EGFR, a receptor tyrosine kinase, is often upregulated in cancers such as non-small-cell lung cancer." (PMID 36671501, 2023). "Below, we summarize the useful information on the evolution of protein degradation to eliminate the wild-type and mutant EGFR in cancer cells." (PMID 37754201, 2023).